USF2 (upstream transcription factor 2, c-fos interacting)
Description:
Transcription factor that binds to a symmetrical DNA sequence (E-boxes) (5'-CACGTG-3') that is found in a variety of viral and cellular promoters.
Synonyms: bHLHb12; FIP
Tractability: PROTAC: ubiquitination databases record sites on it; its protein half-life has been measured.
Gene: Protein-coding gene on chromosome 19 (35,268,962 to 35,279,821, forward strand). Ensembl gene ENSG00000105698.
Subcellular location: Nucleus
Subcellular location (Human Protein Atlas): Nucleoplasm; Vesicles
Pathways (Reactome):
Signal Transduction: Estrogen-dependent gene expression
Gene Ontology:
Molecular function: bHLH transcription factor binding; DNA-binding transcription activator activity, RNA polymerase II-specific; DNA-binding transcription factor activity, RNA polymerase II-specific; E-box binding; protein binding; protein heterodimerization activity; protein homodimerization activity; sequence-specific double-stranded DNA binding; DNA-binding transcription factor activity; RNA polymerase II cis-regulatory region sequence-specific DNA binding; DNA binding; protein dimerization activity
Biological process: cellular response to glucose stimulus; glucose mediated signaling pathway; positive regulation of transcription by RNA polymerase II; late viral transcription; lipid homeostasis; regulation of transcription by RNA polymerase II
Cellular component: nucleoplasm; nucleus; chromatin
Genetic constraint (gnomAD): Loss-of-function variants: 16 observed, 34.21 expected, observed/expected ratio (o/e) 0.47, 90% interval 0.32 to 0.71. The synonymous counts are far from expectation, so gnomAD's model fits this gene poorly and the ratio says little. Missense variants: 387 observed, 393.23 expected, observed/expected ratio (o/e) 0.98, 90% interval 0.9 to 1.07. Synonymous variants: 230 observed, 165.34 expected, observed/expected ratio (o/e) 1.39, 90% interval 1.25 to 1.55.
Homologues: Orthologues: dog USF2 (98% identical), mouse Usf2 (98% identical), pig USF2 (98% identical), guinea pig USF2 (96% identical), chimpanzee USF2 (92% identical), rat Usf2 (89% identical), rabbit USF2 (88% identical), macaque USF2 (87% identical), tropical clawed frog usf2 (77% identical), zebrafish usf2 (71% identical). Paralogues in human: USF1 (49% identical), SREBF2 (29% identical), SREBF1 (27% identical).
Diseases named in the same sentence as USF2 in open-access papers:
USF2 is named in the same sentence as 65 diseases in open-access papers, as found by Europe PMC text mining. Sharing a sentence is not in itself a finding about the gene and the disease. The quoted sentences say what the papers report.
breast carcinoma (12 papers, 2014 to 2025). "Indeed, it has been shown that USF2 is a phosphoprotein and that a number of tumor entities such as prostate cancer, hepatocellular carcinoma and breast cancer are associated with an aberrant USF2 function." (PMID 31013770, 2019). "The loss of transcriptional activity of USF2 in breast cancer cell lines has been reported." (PMID 27625789, 2016). "Studies have shown that USF2 plays a promoting role in the development of breast cancer, colorectal cancer and lung cancer." (PMID 35255935, 2022). "Further opposition comes from other investigation showing that USF2 inhibits the transcriptional activity of Smurf1 and Smurf2 to promote breast cancer cells proliferation, migration and invasion." (PMID 36319631, 2022). "It was reported that USF2 was abnormally high expressed in human breast cancers and correlated with cancer progression." (PMID 34116677, 2021). "While few studies support the idea of USF2 being tumor-suppressive with respect to prostate and breast cancer, other studies reported USF2 as being rather cancer promoting like in lung cancer, thyroid cancer, hepatocarcinoma), and, surprisingly, breast cancer." (PMID 31013770, 2019). "While several studies indicated a tumor-suppressive function of USF2 in prostate cancer, breast cancer and oral cancer, a pro-proliferative function of USF2 was observed in lung cancer cells." (PMID 25238393, 2014). "These functional data strongly imply that USF2 might be an integral component of proliferation and migration processes in prostate, hepatocellular and breast cancer cells." (PMID 31013770, 2019). "In addition to EGR1, CD63 and BIRC3 were also found to be associated with breast cancer, while USF2′s role in breast cancer has not been clearly investigated." (PMID 34252628, 2021). "USF2 has been reported to downregulate Smurf1 and Smurf2, thereby regulating the TGF-β pathway in breast cancer." (PMID 35255935, 2022). "Additionally, circACTN4, potentially mediated by USF2, interacts with FUBP1 to facilitate breast cancer progression by upregulating MYC expression." (PMID 39430741, 2024). "Our findings uncover a pivotal mechanism that circACTN4 mediated by USF2 might interact with FUBP1 to promote the occurrence and development of breast cancer via enhancing the expression of MYC." (PMID 34116677, 2021).
hepatocellular carcinoma (7 papers, 2010 to 2023). A malignant tumor that arises from hepatocytes. "In conclusion, our findings reveal that USF2-mediated upregulation of TXNRD1 contributes to hepatocellular carcinoma progression by activating Akt/mTOR signaling." (PMID 36319631, 2022). "In summary, we provide novel evidence that USF2-mediated upregulation of TXNRD1 contributes to hepatocellular carcinoma progression by activating Akt/mTOR signaling." (PMID 36319631, 2022). "In Hep3B hepatoma cells, upstream stimulatory factor 2 (USF2), a basic helix-loop-helix-leucine-zip transcription factor, cooperates with HIF-2α to promote the hypoxic activation of HIF-2α target genes, including CITED2, EPO, and PAI-139." (PMID 30478339, 2018). "Whole genome ChIP-chip analyses in human HepG2 hepatoma cells showed that USF1/USF2 bind predominantly to CACGTGAC elements." (PMID 25741280, 2015).
prostate carcinoma (7 papers, 2014 to 2023). A carcinoma that arises from epithelial cells of the prostate gland. "Further, not only the oncogenes c-Myc and Ras, whose function could be counteracted by USF2 have been implicated in prostate cancer, but also tumor suppressor genes." (PMID 25741280, 2015). "Recent investigations with a mouse in vivo xenograft model further substantiated the inhibitory role of USF2 since overexpression of USF2 in prostate cancer cells inhibited the tumorigenicity of these cells." (PMID 25741280, 2015). "Similar findings were obtained with respect to USF2; being tumor suppressive with respect to prostate cancer but being rather promoting in the development of lung cancer and thyroid cancer." (PMID 25238393, 2014). "GSK3β appears to be an attractive candidate kinase for the regulation of USF2 since both proteins seem to be involved in the development of different types of cancer, especially prostate cancer." (PMID 25238393, 2014). "Overexpression of USF2 was linked to rheumatoid arthritis that is refractory to treatment through upregulation of proinflammatory cytokines, while stabilization of USF2 protein by CDK5-dependent phosphorylation promotes prostate cancer proliferation." (PMID 37515158, 2023). "In line with this hypothesis, the authors have shown that the USF2 protein level of several prostate cancer cell lines is markedly decreased and that ectopic expression of USF2 in PC-3 prostate cancer cells inhibits their tumorigenicity." (PMID 25741280, 2015). "In line, many cancer cells including the prostate cancer cell line PC-3 displayed a loss of USF2 transcriptional activity while it was active in non-tumorigenic cells." (PMID 25741280, 2015). "That the action of USF2 as suppressor may be of special importance for prostate cancer was first highlighted by a study investigating hormone refractory prostate cancer samples." (PMID 25741280, 2015). "In addition, USF2 has recently been found to be part of the prostatic factor complex as an androgen receptor cofactor and it was found to be downregulated in human prostate cancer specimens." (PMID 25741280, 2015). "In addition to the experiments in HeLa cells, we were able to show that GSK3β-dependent phosphorylation of USF2 also occurs in HepG2 cells and in the human prostate cancer cell lines LNCaP and PC-3 (data not shown)." (PMID 25238393, 2014).
lung carcinoma (6 papers, 2014 to 2022). "For example, ZHX1 expression was inversely related with those of USF-2 and VEGF-B, which have been associated with the proliferation of lung cancer cells and endothelial cell migration, respectively." (PMID 28152006, 2017). "Contrary to the studies suggesting a tumor suppressor role for USF2 in carcinogenesis, there is one study indicating that USF2 has a pro-proliferative function in lung cancer cells." (PMID 25741280, 2015). "Hence, it is possible that USF2 stimulates HSF2 expression also in lung cancer." (PMID 32408596, 2020). "Although it is not yet known by which mechanisms HSF2 expression is enhanced in lung cancer cells, there is a disease-specific correlation between the high expression of HSF2 and the transcription factor USF2 in A549 lung cancer cells." (PMID 32408596, 2020). "Although none of the following studies investigated the participation and phosphorylation of USF2 directly by PKA, it appeared that cAMP and hence PKA might contribute to colorectal cancer cell proliferation, whereas PKA seems to be anti-tumorigenic in lung cancer cells." (PMID 31013770, 2019).
colorectal cancer (5 papers, 2019 to 2023). A primary or metastatic malignant neoplasm that affects the colon or rectum. "S100A8, a calcium- and zinc-binding protein, is regulated by the TGF-β/USF2 axis and induces epithelial‐mesenchymal in colorectal cancer." (PMID 37564208, 2023). "In colorectal cancer, researchers found that miR-362 may be involved in the regulation of the tumor cell cycle by affecting the expression of E2F1, USF2, and PTPN1." (PMID 32582765, 2020).
chronic myeloid leukemia (4 papers, 2013 to 2025). "miR-10a-5p functions as a TSmiR and regulates the expression of upstream stimulatory factor 2 (USF2) in chronic myeloid leukemia (CML)." (PMID 39796267, 2025). "The downregulation of miR-10a in chronic myeloid leukemia CD34+ cells increases USF2-mediated cell growth and increases the cisplatin resistance of lung adenocarcinoma circulating tumor cells via targeting PIK3CA in the PI3K/Akt pathway." (PMID 34062897, 2021). "Repression of miR-10a can increase the upstream stimulatory factor (USF2) expression and promote the proliferation of chronic myeloid leukemia cells." (PMID 23696417, 2013).
melanoma (4 papers, 2016 to 2025). A malignant, usually aggressive tumor composed of atypical, neoplastic melanocytes. "Pearson regression results from 4 different melanoma databases showed that SOX10 and USF2 were positively correlated with the expression of SMARCA4, yet TBX15 and ETS2 were negatively correlated with the expression of SMARCA4." (PMID 36317703, 2022). "From a list of 113 genes shown to be up-regulated by MITF in melanoma, 23 were up- and 20 down-regulated in NuKO cells, which would suggest that Ap4A-mediated MITF or USF2 activation is not prominent in our data." (PMID 27144453, 2016).
thyroid cancer (4 papers, 2009 to 2019). "On this regard, it has been reported that the rs1867277A allele recruits the USF1/USF2 transcription factors and has been shown to be involved in an allele-specific transcriptional regulation of FOXE1 in thyroid cancer." (PMID 28928994, 2017).
asthma (3 papers, 2014 to 2025). "For the rs10905284 (GATA3), the asthma risk allele (C; proxy rs3802597; r2=0·93) had an effect on upstream stimulatory factor 1 (USF1) and 2 (USF2) binding in various cell types, including airway epithelium." (PMID 30552067, 2019).
Sepsis (3 papers, 2024 to 2025). Sepsis is defined as life-threatening organ dysfunction caused by a dysregulated host response to infection. "It has been noted that USF2 knockdown downregulates THBS1 to reduce pyroptosis and further ameliorate sepsis-induced acute kidney injury." (PMID 40220480, 2025).
chronic periodontitis (2 papers, 2021 to 2024). A chronic inflammatory process that affects the tissues that surround and support the teeth. "Xu et al32 also described the regulatory role of the XIST/USF2/WDR72 axis in the development of periodontitis." (PMID 39105315, 2024). "Three transcription factors, FOS, MEF2C, and USF2, were identified as related to the regulation of the crosstalk genes and were also found to be dysregulated in chronic periodontitis." (PMID 33869630, 2021).
endometriosis (2 papers, 2015 to 2025). The growth of functional endometrial tissue in anatomic sites outside the uterine body. "In contrast, eutopic endometria from endometriosis patients exhibited high USF2 variants protein contents during this stage coincidently with the estrogenic microenvironment described in the eutopic and ectopic endometria of these patients." (PMID 26453052, 2015). "The sustained USF2 variants protein expression during the secretory phase in eutopic endometria from women with endometriosis may participate in the pathophysiology of this disease strongly associated with infertility and its characteristic endometrial invasion to ectopic sites in the pelvic cavity." (PMID 26453052, 2015). "TCF21 interacts with USF2 in endometriotic stromal cells and activates the promoters of SF-1 and estrogen receptor beta, thereby influencing the estrogen pathway in endometriosis." (PMID 40182431, 2025). "Nevertheless, in endometriosis cells, the high USF2, SF-1 and P450Arom protein contents in basal condition were unmodified." (PMID 26453052, 2015). "The sustained USF2 protein expression during the secretory phase in eutopic endometria of women with endometriosis may participate in the pathophysiology of this disease strongly associated with infertility and its characteristic endometrial invasion to ectopic sites in the pelvic cavity." (PMID 26453052, 2015). "Although two types of USF, USF1 and USF2, have been reported, it is USF2 that shows the highest binding activity on SF-1 promoter and its knockdown results in down-regulation of SF-1 and also of its target gene CYP19A1 in ectopic endometrium from endometriosis women." (PMID 26453052, 2015).
gastric cancer (2 papers, 2022). A primary or metastatic malignant neoplasm involving the stomach. "For example, miR-10 regulates the oncogene USF2 in myeloid leukaemia, BDNF in cervical cancer, and Tiam1 in gastric cancer." (PMID 35573695, 2022).
HIV-1 infection (2 papers, 2023). The type species of lentivirus and the etiologic agent of acquired immunodeficiency syndrome (AIDS). "As HIV-1 favors the infection of stimulated T cells, and that the loss of USF1 and USF2 dampens T cell activation, we sought to examine the role of these factors for HIV-1 infection." (PMID 37515158, 2023). "Furthermore, the USF2 disruption limited the initial incidence of HIV-1 infection and reduced the proportion of infected cells that underwent productive gene expression." (PMID 37515158, 2023). "However, after 4 days of infection, the USF2 knockout cells accumulated latent HIV-1 infections at a higher proportion compared to the WT or USF1 KO cells." (PMID 37515158, 2023). "To study the potential role of LysRS in regulating USF2 in HIV-1 infected cells, we examined the mRNA transcript levels of TERT, PTPN6 and TGFb1 when the function of pS207-LysRS was blocked during HIV-1 infection." (PMID 37933844, 2023). "The USF2 gene knockout limited T cell activation to a greater extent than the USF1 knockout, and additionally rendered T cells more restrictive to HIV-1 infection." (PMID 37515158, 2023). "In JurkatS207A cells, the transcription of USF2 target genes PTPN6 and TGFb1 was suppressed during HIV-1 infection compared with JurkatWT cells (top)." (PMID 37933844, 2023). "The Western blot results show slightly increased interaction between USF2 and LysRS upon HIV-1 infection in JurkatWT cells, but not in JurkatS207A cells." (PMID 37933844, 2023).
leukemia (2 papers, 2020 to 2023). A malignant (clonal) hematologic disorder, involving hematopoietic stem cells and characterized by the presence of primitive or atypical myeloid or lymphoid cells in the bone marrow and the blood. "For example, USF2 was associated with progression of leukemia through upregulation of HOXA9, but disruption of USF1 alone had minimal effects." (PMID 37515158, 2023). "Ectopic expression of Hoxa9 rescued impaired leukemia cell proliferation upon USF2 loss." (PMID 33001025, 2020). "Cut and Run analysis revealed the direct occupancy of USF2 at HOXA9 promoter in MLLr leukemia cells." (PMID 33001025, 2020). "USF2 is required to maintain HOXA9 expression in MLLr leukemia." (PMID 33001025, 2020). "Importantly, in SEM cells constitutively expressing ectopic retroviral mouse Hoxa9 (SEMHOXA9), USF2 knock-down had little effect on cell growth, suggesting that HOXA9 is a functional and essential downstream gene of USF2 in USF2-mediated leukemia propagation." (PMID 33001025, 2020). "USF1 and USF2 synergistically regulate HOXA9 expression in MLLr leukemia." (PMID 33001025, 2020). "USF2 depletion selectively downregulated HOXA9 expression in MLLr leukemia cells and impaired cell growth, which could be rescued by ectopic expression of HOXA9 and its partner MEIS1." (PMID 33001025, 2020). "Although our study identified the regulatory function of USF1/USF2 on HOXA9 maintenance and leukemia cell survival in MLLr B-ALL and AML cell lines, other HOXA9-independent functions of USF1/2 cannot be excluded and requires further studies." (PMID 33001025, 2020). "By utilizing the reporter and CRISPR/Cas9 screens, we identified transcription factors controlling HOXA9 expression, including a novel regulator, USF2, whose depletion significantly down-regulated HOXA9 expression and impaired MLLr leukemia cell proliferation." (PMID 33001025, 2020). "In addition, USF1 and USF2 synergistically regulate HOXA9 expression and leukemia survival in OCI-AML2." (PMID 33001025, 2020). "Moreover, the function of USF2 in controlling leukemia progression has not been reported." (PMID 33001025, 2020).
liver cancer (2 papers, 2014 to 2023). An epithelial or non-epithelial malignant neoplasm that arises from the liver. "In addition, we analyzed the mRNA levels of USF2 and STX6 in tumor tissues collected from patients with liver cancer and found that USF2 and STX6 expression levels were negatively correlated." (PMID 37564208, 2023).
osteosarcoma (2 papers, 2022 to 2025). A usually aggressive malignant bone-forming mesenchymal neoplasm, predominantly affecting adolescents and young adults. "Earlier result revealed that lack of USF2 function caused increased cell growth in Saos-2 osteosarcoma cells." (PMID 36319631, 2022). "Although the role of WDR3 in osteosarcoma remains unexplored, it has been found to promote cancer stem cell characteristics by inhibiting USF2-mediated RASSF1A transcription." (PMID 40646517, 2025).
renal cell carcinoma (2 papers, 2020 to 2021). "Therefore, it is also possible that USF2 also participates in the HIF2α-dependent expression of PHD3, OCT-4, NDRG1, TGFA, GLUT1, CCND1 and SLC7A5 in renal cell carcinoma." (PMID 33321829, 2020).
rheumatoid arthritis (2 papers, 2022 to 2023). A chronic, systemic autoimmune disorder characterized by inflammation in the synovial membranes and articular surfaces. "Aberrant expression of USF2 was previously linked to additional human diseases, including rheumatoid arthritis and cancer." (PMID 37515158, 2023).
acute pancreatitis (1 paper, 2023). An acute inflammatory process that leads to necrosis of the pancreatic parenchyma. "Bioinformatics analysis suggests that claudin-4 may be regulated by FOX3 or USF2 and plays an important role in acute pancreatitis, and the variation in claudin-4 expression in PCa and acute pancreatitis needs to be further investigated." (PMID 36959784, 2023).